TNF (tumor necrosis factor)
Diseases named in the same sentence as TNF in open-access papers (continued):
Sharing a sentence is not in itself a finding about the gene and the disease.
Insulin resistance (continued). "Moreover, both short and long sleep durations were related to elevated cortisol, IL-6, and tumor necrosis factor-alpha (TNF-a), which could also partially explain insulin resistance, a central characteristic of MetS." (PMID 38398871, 2024). "In addition to TNF-α, IL-6 acts on adipose tissue to increase leptin secretion, suppress satiety, and increase adipose tissue lipolysis, which, in turn, promotes hepatic gluconeogenesis and hepatic insulin resistance." (PMID 39204094, 2024). "It has been observed that FFA treatment can impair insulin receptor-mediated signal transduction, which may alter GLUT4 translocation and can diminish glucose transport and finally induce cellular insulin resistance via the activated JNK pathway or via TNF-alpha-independent mechanisms." (PMID 37893225, 2023). "However, it was recently reported that the deletion of macrophage TNFα did not influence insulin resistance and hepatic lipid accumulation in obese mice, indicating that macrophages are not the source of TNFα that causes metabolic dysfunction." (PMID 36994095, 2023). "Insulin resistance and abdominal obesity are increasingly viewed as chronic inflammatory conditions, leading to the production of a wide variety of pro-inflammatory cytokines and chemokines, including IL-6, monocyte chemoattractant protein-1, TNF-α and other inflammatory factors." (PMID 37228109, 2023). "Moreover, in mammals it is proved that TNFα induces insulin-resistance, by impairing insulin-stimulated glucose uptake through the inhibition of insulin signaling at the insulin receptor substrate level, but on the other hand, TNFα increases basal glucose uptake in adipose tissue." (PMID 36998471, 2023). "Moreover, one should consider the beneficial effects of some conventional drugs, such as methotrexate and hydroxychloroquine, on glucose metabolism as well as the various effects of bDMARDs, such as tumor necrosis factor, IL-6, or IL-1 antagonists, on insulin resistance." (PMID 36983150, 2023). "Proinflammatory cytokines such as tumor-necrosis factor α (TNF-α) and interleukin-6 (IL-6) not only involved in the pathogenesis of hypertension, but also interfered with the insulin signaling pathways which were associated with insulin resistance and diabetes mellitus." (PMID 37139334, 2023). "Third, anxiety could promote the inflammatory response of patients, and some inflammatory factors, such as interleukin-6 (IL-6) and tumor necrosis factor-α (TNF-α), are risk factors for insulin resistance, which could contribute to insulin resistance, thereby promoting the prevalence of MetS." (PMID 36873213, 2023). "These diets may induce hyperglycemia, which is associated with increased pro-inflammatory cytokines, including IL-6 and TNF-α, leading to insulin resistance by disruptions in insulin signalling and subsequently might increase the risk of the diabetes complications." (PMID 38264289, 2023). "In addition, in animal models of insulin resistance, increased aromatase activity has been demonstrated to be associated with the reduced expression of MCP-1 and TNF-α, thus supporting a role for this enzyme in the regulation of the systemic inflammatory response." (PMID 37189813, 2023). "In addition, insulin resistance is correlated with high levels of tumor necrosis factor-α." (PMID 37763777, 2023). "Similarly, andrographolide reportedly blocked the NF-κB signaling pathway induced by TNF-α in adipocytes, suggesting that it might reduce insulin resistance by modulating the insulin signaling pathway and improving glucose uptake." (PMID 36865924, 2023). "While TNF secretion has been speculated to be involved in the initiation of insulin resistance, much of the research has been performed in high-fat diet-fed animals or with differentiated murine cells lacking cellular interactions, both of which do not mimic human physiology or pathophysiology." (PMID 36766750, 2023).
Insulin resistance (continued). "In addition to lipid and muscle wasting, elevated TNF-α can lead to anorexia, activate skeletal muscle protein degradation, inhibit protein synthesis, induce insulin resistance and mediate systemic inflammation in cancer malnutrition, further exacerbating malnutrition." (PMID 37533569, 2023). "Additionally, disturbances in lipid metabolism accompanied by gut-derived endotoxins promote the production and release of proinflammatory IL-1, IL-6, and TNF-α, which are able to inhibit insulin receptors signaling, aggravating insulin sensitivity and contributing to insulin resistance worsening." (PMID 37998747, 2023). "Also, it has been shown the relative gene expression of pro-inflammatory cytokines such as IL1-β, IL-6, and TNF-α, and apoptosis reduced in insulin resistance-induced HepG2 models after treatment with a combination of metformin and MSC-EXO compared to other groups." (PMID 37153436, 2023). "Various studies determined that IL-6 and TNFα could promote insulin resistance." (PMID 37013538, 2023). "Peripheral insulin resistance is also induced by the inflammatory response and cytokine storm triggered by COVID-19, characterized by significant increases in the levels of inflammatory markers, such as tumor necrosis factor-alpha (TNF-alpha) and interleukin-6 (IL-6)." (PMID 37649125, 2023). "Both TNFα and IL-6 have been extensively studied and reviewed as promoters of an inflammatory response, with local recruitment of immune cells, such as macrophages, which contribute to chronic inflammation, and may in turn lead to insulin resistance in AT." (PMID 35557517, 2022). "In addition, JNK knockdown mice have a decreased expression of pro-inflammatory cytokines such as TNF-α or IL-6, which might protect against insulin resistance in T2DM." (PMID 35455066, 2022). "Acute insulin resistance induced by tumor necrosis factor alpha (TNFα) or dexamethasone could be ameliorated by the antioxidants N-acetylcysteine, manganese (III) tetrakis (4-benzoicacid) porphyrin (MnTBAP), or by induction of antioxidant enzymes such as superoxide dismutase or catalase." (PMID 35625712, 2022). "Furthermore, studies show that TNFα may be involved as a low-grade stimulus of osteoporosis, insulin resistance, and atherogenesis in postmenopausal women which is related to estrogen deficiency." (PMID 36364884, 2022). "The elevated levels of TNF-α emerging due to inflammation may induce insulin resistance." (PMID 35743146, 2022). "Therefore, TNF-α may be indirectly involved in the ACCumulation of triglycerides in the liver, which may also be effective in inducing hepatic insulin resistance." (PMID 36110559, 2022). "The hypertrophic adipocytes secrete pro-inflammatory cytokines such as tumor necrosis factor-α (TNF-α), interleukin 6 (IL-6), interleukin 8 (IL-8), and monocyte chemoattractant protein 1 (MCP-1) which, through the phosphorylation of insulin receptor substrate-1 (IRS-1), cause insulin resistance." (PMID 35406070, 2022). "Moreover, biochemical indicators such as insulin, insulin resistance index, ADP, GLP-1, LEP, FFA, IL-6, and TNF-α in the serum indicated that GG polysaccharide and FG polysaccharide improved insulin resistance and leptin resistance in diabetic mice, as well as chronic inflammation." (PMID 36235582, 2022). "Therefore, the decreased production of IL-4 by Th2 cells and IL-10 from Treg cells within the adipose tissue leads to a relative decline of anti-inflammatory M2 macrophages, while the concurrent increase of Th1 cells promotes TNF-expressing M1 macrophages and hence, insulin resistance." (PMID 35844529, 2022). "Hotamisligil and Spiegelman highlighted the presence of TNF-alpha (a pro-inflammatory cytokine produced mainly by macrophages that stimulates the inflammatory reaction in the acute phase) in adipose tissue and its direct role in promoting the condition of insulin resistance in mice." (PMID 36648872, 2022).
Insulin resistance (continued). "Furthermore, the hypoxic conditions prevailing in early pregnancy stages induce the placental release of proinflammatory factors such as tumor necrosis factor alpha (TNF-α) and interleukin-6 (IL6), which are associated with insulin resistance and endothelial dysfunction." (PMID 35252239, 2022). "It is known that TNFα directly impairs insulin signaling through inhibition of tyrosine kinase activity of the insulin receptor and thus could be a critical mechanism whereby adiposity induces peripheral insulin resistance." (PMID 36364884, 2022). "Thus, we conclude that TNF-α disrupts the regulation of leptin on the β cell GSIS function by inhibiting leptin receptor LepRb and thus producing excessive insulin secretion related to hyperinsulinemia, which is postulated to be a cause of insulin resistance." (PMID 35198097, 2022). "Finally, treatment with VSL#3 probiotics alleviated obesity, hepatic steatosis, and insulin resistance, as well as reduced inflammation, downregulating the activation of TNFα/inhibitor of nuclear factor kappa-B kinase subunit beta (IKK-β) signaling pathway in high-fat diet-fed mice." (PMID 36139402, 2022). "In addition, TNF-α, IFN-γ, and IL-1β are all associated with inflammation and insulin resistance." (PMID 36552805, 2022). "HCT can contribute to the release of several proinflammatory cytokines such as interleukin-6 (IL-6) and tumor necrosis factor-α (TNF-α), and previous studies have shown that the latter could contribute to insulin resistance by influencing the insulin signaling pathway." (PMID 35406580, 2022). "Elevated level of protein carbonylation in dexamethasone-treated (by 110%) and in TNF-α-treated (by 50%) adipocytes reflected cumulative oxidative stress in insulin-resistant cells and pointed that the increase in ROS level precedes and triggers the onset of detectable insulin resistance." (PMID 36246880, 2022). "Anti-inflammatory agents such as salicylates, TNF-α antagonists, IL-1β antagonists, leukotrienes, and CA may be useful in developing therapeutics for obesity-related diseases, including insulin resistance, type 2 diabetes, and atherosclerotic cardiovascular disease." (PMID 36015301, 2022). "It has been reported that TNF-α is the key mediator of insulin resistance because it can reduce insulin signaling by potently inhibiting insulin receptor (IR) tyrosine kinase, which might reduce the ability of IRS-1 to transduce signals in the insulin signaling system." (PMID 35320949, 2022). "Importantly, there is a large amount of evidence for a role for TNFα in insulin resistance." (PMID 36078455, 2022). "However, increased TNFα also occurs with increasing insulin resistance." (PMID 35966095, 2022). "However, it is unknown whether the beneficial effect of exercise on insulin resistance involves in TNF-α level regulated by vagus nerve-related anti-inflammatory activity in the spleen." (PMID 34717724, 2021). "A pathogenetic link between psoriasis and T2DM could be traced primarily in the increase in psoriasis of TNF-α, a pro-inflammatory cytokine which plays an important role in the pathogenesis of insulin resistance, through the reduction of the tyrosine-kinase activity of the insulin receptor." (PMID 33834030, 2021). "Pro-inflammatory mediators (e.g., tumor necrosis factor-alpha, TNFα and interleukins (IL) 1 and 6) impair adipose tissue function in an auto- and paracrine manner but also influence other tissues, contributing to the development of insulin resistance and other components of metabolic syndrome." (PMID 34943849, 2021). "Moreover, chitosan supplementation could also reduce the concentration of TNF-α, which might improve insulin resistance, thereby reducing insulin secretion." (PMID 34443619, 2021).
Insulin resistance (continued). "Additionally, B12 deficiency has been shown to be linked with elevated levels of pro-inflammatory cytokines (such as tumor necrosis factor-alpha (TNF-α) as and biochemical markers related to cardiometabolic risk (glycemia, insulin resistance and lipid profile parameters) in T2DM." (PMID 33784336, 2021). "Moreover, inflammatory markers (interleukin 6, interleukin 1β, and tumor necrosis factor α), insulin sensitivity (fasting glucose, insulin, and homeostatic model assessment for insulin resistance index), and lipid profile (cholesterol, HDL, and LDL) significantly improved after TRE compared with ND." (PMID 34649266, 2021). "Thus, we propose that the insulin sensitizing effect of BME on the TNF-α-treated enterocytes may be a result of its anti-inflammatory function, ameliorating inflammation-induced insulin resistance." (PMID 33746602, 2021). "However, whether apM1 and TNF-α genes influence the development of metabolic syndrome (MetS) preceded by insulin resistance is unclear." (PMID 33997011, 2021). "Furthermore, mice genetically deficient in TNF-α or the TNF receptor 1 gene do not develop insulin resistance, even under elevated fatty or obese circumstances." (PMID 34745386, 2021). "Also, chronically elevated levels of inflammatory cytokines such as CRP, TNF-a, IL-6, and IL-1b could enhance insulin resistance (IR), disrupt insulin sensitivity, and consequently impair glucose homeostasis resulting in an increase in the risk of T2DM." (PMID 34917685, 2021). "Insulin resistance at the beginning of gestation results from changes in maternal hormones; secretion of placental proinflammatory markers including leptin, resistin, and tumor necrosis factor-alpha (TNF-α); and reduction of anti-inflammatory factors such as adiponectin." (PMID 33552314, 2021). "In addition, increased levels of pro-inflammatory cytokines such as TNF-a, IL-8 and IL-6 have been reported in pregnancy complicated by GDM, suggesting that proinflammatory cytokines could be involved in the development of insulin resistance associated to GDM." (PMID 33477354, 2021). "Globally, apart from psoriatic disease, TNF-α is known to induce insulin resistance both in vitro and in vivo, by reducing tyrosine kinase activity of the insulin receptor, and endothelial dysfunction, and it may contribute to altered cardiac remodeling after myocardial infarction." (PMID 34829740, 2021). "Moreover, IL-6 and TNF may stimulate the breakdown of adipose tissue in an organism through the decrease in fodder consumption, induction of insulin resistance, and direct initiation of lipolysis." (PMID 34316205, 2021). "Interestingly, circulating levels of TNF-α have been shown to be positively correlated to maternal insulin resistance, suggesting that placental EVs may modulate insulin sensitivity during gestation." (PMID 34769262, 2021). "Additionally, a HFD induces insulin resistance and increases TNF-α expression." (PMID 34357066, 2021). "Therefore, it can be hypothesized that in the present study the persistence of increased levels of LPS and TNFα could participate in the maintenance of insulin resistance in the liver of FR rats." (PMID 33921866, 2021). "Furthermore, a positive correlation was reported between the level of TNF-α and insulin resistance." (PMID 34239559, 2021). "Thus, the pro-inflammatory factor TNF-α obviously induced insulin resistance in IEC-18 cells." (PMID 33746602, 2021).
Insulin resistance (continued). "Physical exercise, in turn, moderates the inflammatory condition, decreasing the secretion of leptin and TNF-α, which is a metabolic cascade of changes in other adipokines, it reduces the secretion and cytokines of the insulin antagonist and subsequently improves insulin resistance." (PMID 34568974, 2021). "Additionally, the development of insulin resistance is contributed to by pro-inflammatory cytokines such as tumor necrosis factor α (TNF-α), interleukin 1 (IL-1), and interleukin 6 (IL-6), which affect insulin signaling by inhibition of IRS-1 through serine phosphorylation." (PMID 34299269, 2021). "Besides, compared with obese NAFLD patients, non-obese individuals with NAFLD had a substantially lower polyunsaturated fatty acid intake, which can ameliorate the activity of NAFLD through reducing hepatic TNF-α expression and improving insulin resistance in animal models." (PMID 33608033, 2021). "The results of this experiment showed that in the T2DM mice, insulin resistance could delay the progression of T2DM by promoting the expression of TNF-α and MCP-1 inflammatory factors, while KRS treatment significantly inhibited the upregulation of inflammatory factors." (PMID 34691353, 2021). "In addition to the redistribution of lipids, PPARγ also inhibits the synthesis of tumor necrosis factor α (TNFα) and resistin, both related to inflammation and insulin resistance, while inducing the synthesis of adiponectin, which favors the oxidation of fatty acids." (PMID 33946267, 2021). "Similarly, the significant enrichment scores of pathways involved in DNA strand elongation and mitotic processes further support our hypothesis that TNFα not only leads to insulin resistance, but also induces cell cycle progression." (PMID 34576943, 2021). "Various proinflammatory factors or cytokines are activated due to insulin resistance, including nuclear factor-kappaB (NF κB), tumour necrosis factor-alpha (TNF-α), amylin and interleukin-6, and these proinflammatory factors may be responsible for the initiation and progression of AP." (PMID 33407178, 2021). "Indeed, it has been demonstrated that anti-TNF therapy improves insulin resistance." (PMID 34631754, 2021). "Moreover, hyperglycemia in diabetes could be controlled by GNPs via improving blood glucose levels, insulin resistance, and liver enzymes, reducing proinflammatory cytokines (include TNF-α, IL-6, and CRP), and enhancing the antioxidant defense enzymes." (PMID 34572503, 2021). "TNF-α signaling activates intracellular kinases, c-Jun N-terminal kinase and IκB kinase, leading to increased serine phosphorylation of insulin receptor substrate-1 (IRS-1) which impairs insulin signaling, causing insulin resistance that inhibits the transport of glucose into cells." (PMID 33208757, 2020). "Moreover, TLR2 and TLR4 activity was markedly increased in association with elevated TNF-α, IL-6, and IFN-γ expressions, increased insulin resistance in response to inflammation; the changes were more prominent in diabetic patients with end-stage renal disease and renal failure." (PMID 33442388, 2020). "This decrease in TNF-α protein expression might act to reduce inflammation and insulin resistance." (PMID 33266423, 2020). "Previous in vivo evidence showed that obese FABP4-deficient mice would not develop insulin resistance or diabetes since they could not express tumor necrosis factor-α (TNF-α) from adipose tissues." (PMID 33287461, 2020). "The increase in insulin may also be as a result of insulin resistance which is also supported by the observed significant increase in TNF-α (TNF-α induces insulin resistance by inhibiting insulin signal transduction) and leptin levels (females only) in sugar fed rats compared to honey fed ones." (PMID 32153977, 2020).